MUC1 (mucin 1, cell surface associated)
Diseases named in the same sentence as MUC1 in open-access papers (continued):
Sharing a sentence is not in itself a finding about the gene and the disease.
tumor (continued). "Similarly, MUC1-CAR-Ms showed potent phagocytosis and inflammatory cytokines release when co-cultured with MUC1-expressing tumor cells." (PMID 41309977, 2025). "This contrasts with free MUC1, which did not result in significantly different tumor sizes compared to PBS controls." (PMID 40284463, 2025). "When mice were vaccinated with C3-liposomes containing TLR agonists and no MUC1, tumor growth was significantly reduced compared to PBS controls." (PMID 40284463, 2025). "Many pan-cancer tumor targets, including human epidermal growth factor receptor 2 (HER2), mucin 1 (MUC1), and EGFR, are also expressed at high levels in UCs and may serve as therapeutic targets." (PMID 38789450, 2024). "Since the communication between tumour cells and CAFs, unveiled by single‐cell transcriptomics, was mediated by MUC1 and FGF7/THBS1 to a certain degree, we examined the possibility of crosstalk between these two cell types in tumour tissues through expression information in spatial transcriptomics." (PMID 38778448, 2024). "Notably, plasma MUC1 was significantly elevated in FIGO II compared to FIGO I, thus supporting the idea that circulating CA15-3 increases with tumour burden." (PMID 39020428, 2024). "Meanwhile, the membrane-bound mucin glycoprotein (Muc-1), indoleamine 2,3-dioxygenase (IDO) and soluble primary histocompatibility complex class I -related chain A (sMICA) suppress innate and adaptive immunity and play an essential role in tumor prognosis." (PMID 38464531, 2024). "The reticular structure formed by the secreted mucus, as well as the extraordinary size of heavily O-glycosylated membrane-bound mucins such as MUC1 or MUC4, are capable of limiting drug intracellular entrance and immune recognition of tumor cell epitopes in antibody-based therapies." (PMID 38380362, 2024). "In patient-derived xenotransplantation models, anti-MUC1 CAR-T cells have not been found to significantly inhibit the growth of NSCLC tumours." (PMID 38475858, 2024). "Unlike tumor-associated antigens, neoantigens such as epidermal growth factor receptor variant III (EGFRvIII) and Tn glycoform of MUC1 are absent in normal tissues and considered "non-self"." (PMID 38918817, 2024). "The targeting ligands can identify a variety of representative tumor biomarkers, such as FR, TfR, insulin receptor (IR), estrogen receptor α (ERα), prostate-specific membrane antigen (PSMA), mucin-1 (MUC1), nucleolin, and human epidermal growth factor receptor 2 (HER2)." (PMID 39204392, 2024). "The results showed that siMUC1 tumour cells did not induce macrophage polarisation toward the M2 phenotype, and MUC1 knockdown led to a decrease in the cytokines ICAM and IL6." (PMID 38778448, 2024). "In addition, we performed paired analysis of RNA sequencing and IHC data of patient-derived tumor xenograft (PDX) samples, and estimated that EGFR and MUC1 were expressed in 97.5% of LUAD samples of The Cancer Genome Atlas Program (TCGA) database." (PMID 39664199, 2024). "Those in vivo results are supported by in vitro experiments, wherein dendrimers were selective to MUC-1 positive cell lines (C26 and HT29) and further supported by CT scans, which showed increased intensity at the tumor site after treatment with Apt-PEG-AuPAMAM-CUR." (PMID 38399238, 2024). "Consistent with the results from non-tumor samples, all the TIMGs that we identified (ENO1, MUC1, COL5A1, COL11A1, IL11, AIM2, JUNB) as well as FABP7, exhibited significantly or moderately elevated expression in multiple TCGA tumors, including GBM, compared to normal tissues." (PMID 39596296, 2024).
tumor (continued). "Taken together, IHC analysis demonstrated that EGFR and MUC1 were present at medium to high levels in the majority of LUAD and CRC samples, and in line with single-cell analysis, they tended to be co-expressed on tumor cells." (PMID 39664199, 2024). "Furthermore, MUC1 overexpression not only increases the resistance to anoikis, one main feature of CSC, but also circulating tumor cells (CTCs)." (PMID 38254882, 2024). "This suggests that high expression of MUC1 and MUC16 aids tumor cell immune evasion." (PMID 38361923, 2024). "Actually, MUC1 and many other CAR-combining antigens used in immune cell therapy are tumor-associated antigens (TAA) rather than tumor-specific antigens (TSA)." (PMID 38390321, 2024). "The therapeutic potential of 139H2 therefore lies in targeting the characteristic overexpression of MUC1 in tumor cells, not the aberrant MUC1 glycosylation that is commonly described in MUC1-overexpressing cancers." (PMID 38508723, 2024). "In addition to inhibiting tumor growth, the MF59 and CpG compound adjuvant also triggered a Th1 immune response through the mucin 1 (MUC1)-maltose-binding protein (MBP) (MM) vaccine, leading to increased survival time in both preventive and therapeutic mice." (PMID 38322258, 2024). "Additionally, tumor tissue analysis revealed a significant decrease in ICAM1, MMP9 and MUC1 expression following atorvastatin treatment, along with inhibited MAPK pathway activation." (PMID 38907234, 2024). "In addition, MUC1 binds to HIF-1α and P300 in a hypoxic-dependent manner and acts as a metabolic regulator to help tumor cells survive and proliferate under such conditions." (PMID 38164273, 2024). "MUC1 serves a pivotal role in EOC, significantly influencing tumor metastasis and progression." (PMID 39033780, 2024). "Of note, the virus replicates in tumor cells that are defective in the Rb/p16 pathway and therefore oncolysis is not dependent on MUC1 expression." (PMID 38910324, 2024). "MUC1 is a type I transmembrane protein that is overexpressed in most human epithelial cancers and is involved in epithelial–mesenchymal transition (EMT) and tumor progression." (PMID 39201386, 2024). "Dysregulated expression and glycosylation of MUC1 and MUC16 in cancer, notably affecting immune modulation and metastasis, impair dendritic cell function, resulting in heightened immunosuppression and advancing tumor progression." (PMID 38361923, 2024). "A recent study found that in MUC1.Tg mouse models, peptide vaccination consisting of two different 9-polymers derived from MUC-1 combined with CpG oligonucleotides and granulocyte–macrophage colony–stimulating factor (GM-CSF) as adjuvants reduced tumor load." (PMID 38918278, 2024). "Additionally, several studies demonstrated that upregulated MUC1 and MUC4 expression plays an important role in tumor cell metabolism, mesenchymal transition, apoptosis, and metastasis (Qing, Li & Dong, 2022)." (PMID 38274327, 2024). "We used two human PDA cells lines that constitutively express high MUC1 (CFPAC and HPAFII) along with six pairs of isogenic human and murine tumor cell lines and stably transfected them with either an empty vector or full length MUC1, designated as "Neo" and "MUC1", respectively." (PMID 38326371, 2024). "The expression level of MUC1 is markedly elevated in malignant tumor cells, which are nonpolarly distributed on the surface and cytoplasm of the epithelial cells." (PMID 39491020, 2024). "Focusing on CRC patients with high tumor purity from the TCGA database, we found a resistant oncogenic signature of immune evasion (including REG4, CTSE, MUC1, TFF2, LCN2) that inversely correlated with cytotoxicity and immune infiltration deconvolution scores (T- and NK-cells)." (PMID 39632825, 2024). "We therefore analyzed MUC1 expression in the (i) QGP-1 pNET cell line isolated from the primary lesion of a patient with liver metastases and (ii) BON-1 pNET cell line derived from a primary tumor with metastases to lymph nodes." (PMID 39062082, 2024).
tumor (continued). "In this model, vaccination with MUC1 DNA + BMDCs was effective in overriding MUC1 tolerance and reducing the tumor burden by a mechanism not affecting the level of colonic inflammation." (PMID 36980805, 2023). "In this scenario, we evaluated the PTX3 expression and analyzed the potential role of complement system activation on tumor site and immune microenvironment modulation, stratifying samples in tumors with high (MUC1H) versus tumors with low MUC1 expression (MUC1L)." (PMID 36902242, 2023). "Our qRT-PCR analysis showed that MUC1 expression levels in the tumour tissues were 1.7-fold higher than that in the tumour-far normal tissues (p < 0.0001), consistent with upregulation of EGFR gene expression in the same tumour tissues (p < 0.0001)." (PMID 36810913, 2023). "However, other MUC1-specific mAbs, such as huHMFG1, hPAM4, BrE-3, and CMB-401, always showed limited anti-tumor activity as a monotherapy in clinical studies." (PMID 37489369, 2023). "Using a coculture in vitro system set up between ASCs and two different human ACC cell lines, H295R and MUC-1, we reproduced this condition in vitro to study the reciprocal modulation of CAIII and CAIX in cancer and adipose cells, mimicking the adipose tumor microenvironment." (PMID 36646964, 2023). "Among them, MUC1, MUC5AC, MUC4 and MUC16 are abnormally expressed in the early stages of PanIN, and the expression increases as the cancer progresses through carcinogenesis and tumor invasion." (PMID 37304241, 2023). "The isolated peripheral T cells can be genetically engineered to target several known tumor antigens of HNSCC, including, EGFR, MAGE-A4, MUC1, CD 70, and HER2, and the ACT with these agents has demonstrated a durable clinical response in early clinical studies." (PMID 36992219, 2023). "In the multi-gene assay-cohort, tumors with apical patterns had the lowest recurrence scores, reflecting lower tumor malignancy, and were significantly lower than MUC1-negative tumors (P = 0.038)." (PMID 37002293, 2023). "One positive aspect of this CAR-T cell is that the variable region only recognizes MUC1*, which is only present on tumor cells, and not MUC1, which is also present in healthy tissue, decreasing the “on-target, off-tumor” effects." (PMID 37046648, 2023). "When ASCs were stimulated to differentiate toward adipocytes, a significant reduction in CA3 in the presence of H295R cells and a slight increase in the presence of MUC-1 was evident compared to adipogenesis stimulated without tumor cells." (PMID 36646964, 2023). "Tumor-associated MUC1 binds SIGLEC9, thus mediating tumor cell growth and inducing negative immunomodulation." (PMID 37133224, 2023). "In contrast to the C1/MES subtype, the C4/DIF molecular subtype was described as having a low stromal response histologically and genetically, moderate immune infiltration in tumor and stroma and expression of markers of differentiation including E-cadherin, MUC16 and MUC1." (PMID 37858159, 2023). "The IgGs bound hyperglycosylated MUC1 on human cancer cell lines and tumor tissues but showed no reactivity against fully glycosylated MUC1 on normal cells and tissues; in addition, these antibodies are able to induce antibody-dependent cytotoxicity." (PMID 37514155, 2023). "Despite a statistically significant difference between neoplastic and paracancerous tissues, MUC1 was not selectively expressed by tumor cells." (PMID 37760554, 2023). "In addition, tumor cells promote different signaling pathways that are involved in growth, survival, and EMT by increasing Muc1 expression on their surface." (PMID 38004422, 2023). "With this aim, we designed this retrospective study to demonstrate profiles of MUC expression (MUC1, MUC2, MUC5AC, and MUC6) of different histologic patterns within the same tumor among pulmonary adenocarcinomas and investigate correlations of MUC expression with clinicopathologic features." (PMID 36367122, 2023).
tumor (continued). "Both autologous and allogenic MUC1-Tu-sEVs stimulated immune responses and inhibited tumor growth 2-fold greater than control Tu-sEVs, independent of their MHC types in vivo." (PMID 37681880, 2023). "The final tumor stages were more advanced in patients with MUC1 expression than in those without MUC1 expression (p < 0.001)." (PMID 36831343, 2023). "Furthermore, MUC1 was negatively correlated with CD8+T and Treg cells in the metastatic tumor microenvironment and positively correlated with DC." (PMID 36738352, 2023). "All BC cell subtypes and 95% of all TNBCs overexpress an aberrant glycosylated tumor form of MUC1 (tMUC1) that is not significantly expressed in normal breast cells and tissues." (PMID 37457288, 2023). "It has been demonstrated that Gal-3 coincided with that of MUC1 on the surface of various human tumor tissues, but not in human nonmalignant cells." (PMID 37345016, 2023). "We designed this retrospective study to demonstrate profiles of MUC expression (MUC1, MUC2, MUC5AC, and MUC6) of different histologic patterns within the same tumor among pulmonary adenocarcinomas and investigate correlations of MUC expression with clinicopathologic features." (PMID 36367122, 2023). "The protein complex of Galectin-3-TF/MUC-1 induces MUC-1 cell surface polarization leading to the exposure of cell adhesion molecules, thus inducing tumor cell adhesion to the vascular endothelium which increases the number of cancer cell aggregates in the circulation." (PMID 36873388, 2023). "While the MUC1 sequence does not contain any tri-Ser repeats, other mucins overexpressed on tumor cells do." (PMID 36845552, 2023). "The expression of different mucins, like MUC1, MUC4, and MUC16, which are upregulated during cancer progression, may also inhibit apoptosis of tumor cells." (PMID 37207152, 2023). "The proportion of tumor histological type by the Lauren classification was not different according to the MUC1 expression level." (PMID 36831343, 2023). "To date, MUC1 and MUC16 have been reported to be specific tumor antigens for Siglec-9." (PMID 37444515, 2023). "Using these tumor samples, we also detected the expression of KK-LC-1, MAL2 and MUC1." (PMID 36895039, 2023). "Notably, the tumor volumes and tumor weights when treated with SZU251 + MUC1 + Al were much lower than when treated with SZU251 + Al or MUC1 + Al." (PMID 36499455, 2022). "Notably, in the pancreatic cancer mouse model inoculated with Panc02-MUC1-PDL1, the tumors of the tumor-bearing mice immunized with PBS-DCs, PDL1-DCs and MUC1-Vax DCs appeared to vary degrees of tumor reduction." (PMID 35891256, 2022). "The complex carbohydrates attached to the membrane proteins and extracellular matrix proteins, such as E-cadherin, integrins, Mucin1 (MUC1), and CD44, alter the structure and function of the glycoproteins, as well as intracellular signaling, to promote tumor metastasis." (PMID 35752750, 2022). "The joint activation of these G protein-coupled receptors induces the activation of the tyrosine-kinase effector GSK3 to induce cell proliferation, cell migration, and colony formation possibly via alteration of MUC1, NOTCH, and STAT3 expression resulting in a more aggressive tumor profile." (PMID 35568869, 2022). "Large glycoproteins (such as MUC1 and CD44) are abundantly expressed on circulating tumour cells isolated from patients with metastatic breast cancer that indicated a bulky glycocalyx on tumour cells could favour tumour cell dissemination and metastasis." (PMID 35260891, 2022). "MUC1 also encodes the oncogenic MUC1-C subunit, which we found by immunohistochemistry (IHC) is expressed in MCCP and MCCN tumor, and not surrounding normal, tissues." (PMID 35688945, 2022). "Furthermore, exogenous expression of MUC1 and MUC13 rescued the ability of YBX1−/− PDAC cells to grow a tumour in the pancreas." (PMID 35292781, 2022).
tumor (continued). "Similarly, anti-MUC1 and CD3 bispecific antibodies were also capable of inhibiting tumour growth, although they have been significantly less studied than anti-GD2 bispecific antibodies." (PMID 35454762, 2022). "In contrast, studies using MUC-1–targeted CAR-T cells in patient xenograft model did not reveal significant suppression of NSCLC tumor growth." (PMID 35720364, 2022). "TTF-1 promoter, glypican-3 protein (GPC3), human secretory leukocyte protease inhibitor (hSLPI), Mucin 1 (MUC1), cyclooxygenase 2 (COX2), epithelial glycoprotein (EPG2), and human telomerase reverse transcriptase (hTERT) are the most common tumor-specific promoters used in transcriptional targeting." (PMID 36311790, 2022). "Involvement in the growth and death of cancer cells is not the only way that MUC1 promotes BC tumor progression." (PMID 35248049, 2022). "No obvious inflammatory reactions were found after analysis, indicating that this novel MUC1-Vax vaccine has no pathological toxicity to immunized mice and is a relatively safe and effective tumor vaccine." (PMID 35891256, 2022). "Finally, a detailed report on the establishment of ACC tumor spheroids and organoids including NCI-H295R, MUC-1 and TVBF-7 in a high-throughput format is currently under review." (PMID 35764904, 2022). "MIN-C2 and MIN-E6, two mouse IgG antibodies, are capable of recognizing a 45-AA membrane-proximal extracellular region in MUC1 (PSMGFR) on MUC1-expressing tumor cell surfaces, rather than on human stem cell surfaces." (PMID 35883508, 2022). "In a therapeutic setting, the quantification of Ki-67 indices revealed significant anti-proliferative effects of adavosertib, a small molecular Wee1-inhibitor, against MUC-1 but not NCI-H295R tumor spheroids." (PMID 35879289, 2022). "Most TAAs refer to overexpressed tumor antigens, for example, the receptor for advanced glycation endproducts-1 (RAGE-1), human telomerase reverse transcriptase (hTERT), human epidermal growth factor receptor 2 (HER2), mesothelin, and mucin 1 (MUC1)." (PMID 35456701, 2022). "In contrast, for MUC-1 which was also derived from a male patient tumor originally diagnosed as hormonally diffuse with no clinical signs of steroid excess at baseline no parameter of steroid excess was detectable." (PMID 35563746, 2022). "MUC1 was expressed in the inner luminal surface of IDC glandular ducts and on the mesenchymal side of IMPC tumor cell clusters, leading to the formation of unconnected gaps between IMPC tumor cell clusters and interstitial tissues, which are easily detached." (PMID 35013309, 2022). "One of the previous studies demonstrated the target‐specific cytotoxicity of anti‐Tn‐MUC1 (Tn glycol‐form of MUC1) CAR T cells, which could successfully control tumor growth." (PMID 35102706, 2022). "MUC1 is abnormally up-regulated in estrogen receptor-positive breast cancer and produces tamoxifen resistance through receptor tyrosine kinases (RTK), B-catenin, and E-cadherin to mediate tumor growth control in response to tamoxifen." (PMID 36359853, 2022). "A schematic diagram illustrates our current understanding of MUC1’s role in switching TGF-β signaling from a canonical tumor suppressive to a non-canonical tumor promoting pathway." (PMID 35237602, 2022). "It is designed to target MUC1, which is overexpressed and aberrantly glycosylated in NSCLC, and induce a cellular immune response that may lead to immune rejection of tumor tissues that express the MUC1 antigen." (PMID 35214699, 2022). "Therefore, several groups worked on CAR T cells; for example, in one study, anti-MUC-1 specific CAR T cells were produced and showed significant anti-tumor activity and cytotoxicity in TNBC in vivo and in vitro." (PMID 35000604, 2022).